PIK3CA (phosphatidylinositol-4,5-bisphosphate 3-kinase catalytic subunit alpha)
Diseases named in the same sentence as PIK3CA in open-access papers (continued):
Sharing a sentence is not in itself a finding about the gene and the disease.
breast cancer (continued). "High levels of both AREG mRNA and protein were correlated with the mutation status of PIK3CA in breast cancer cell lines." (PMID 34207383, 2021). "The results of these studies indicate the importance of mutations in the PIK3CA gene in various types of breast cancer." (PMID 33669698, 2021). "For example, gain of function mutations in PIK3CA have been suggested to be associated with trastuzumab/lapatinib resistance by up-regulating PI3K pathway in breast cancer." (PMID 34399705, 2021). "In breast cancer, PIK3CA mutations are present in about a third of patients and are more common in ER-positive, HER2-negative cancers." (PMID 33435133, 2021). "PIK3CA is the most frequently mutated gene in this pathway with mutations occurring in about 20% of HER2-amplified breast cancers." (PMID 34344439, 2021). "Alpelisib has been approved by the FDA for the treatment of HER2-positive advanced breast cancer with a PIK3CA mutation, which increases the 7.9-month survival rate of patients with advanced breast cancer, according to a phase III clinical trial (NCT04208178)." (PMID 34279440, 2021). "In contrast to hotspot mutations in oncogenes like PIK3CA, which are very potent, most of the gCIS identified in our functional genomic screen likely contribute to mammary tumor formation in more subtle and conditional ways." (PMID 34475389, 2021). "PIK3CA is a highly frequently mutated or amplified gene in cervical cancer, head and neck cancer, breast cancer, lung cancer, neuroblastoma, and other malignant tumors." (PMID 34249689, 2021). "Another study revealed that PIK3CA-mutated HR+/Her2− breast cancer patients had a poor outcome and resistance to chemotherapy." (PMID 34367282, 2021). "PIK3CA, which is the most frequently mutated gene in breast cancer, was predominantly altered in luminal tumors and was mutated at a much higher frequency in LumA (45%) relative to LumB (29%) tumors." (PMID 33669749, 2021). "Further study is necessary to find the role of PIK3CA mutation in the regulation of downstream molecules to improve our understanding and therapeutic approach for canine mammary tumors." (PMID 34359206, 2021). "The PIK3CA mutation frequency significantly differed among the four breast cancer molecular subtypes, with 48.3% (155/321) in HR+/HER2-, 45% (50/111) in HR+/HER2+, 42.2% (27/64) in HR-/HER2+, and 25% (17/68) in HR-/HER2- patients." (PMID 34093841, 2021). "Our results from in vitro and in vivo experiments showed that Melatonin significantly enhances the cytotoxicity of Neratinib in a panel of HER2+ breast cancer cells harboring PIK3CA mutations known to be less responsive to HER2-targeted agents." (PMID 34556812, 2021). "This association was especially significant for the breast cancer cell lines harboring mutant PIK3CA when PTEN was exogenously knocked out (EFM19, T47D, MCF-7, MDA-MB-453, and BT20)." (PMID 34417459, 2021). "PIK3CA mutations in operable primary breast cancer also indicated a significant correlation with better disease-free survival (DFS) as well as a better recurrence-free survival in the Luminal A subtype." (PMID 34298731, 2021). "Of interest, of the three patients with metaplastic breast cancer, two patients who had somatic PIK3CA mutation responded with a residual 4 mm (patient #1) and 8 mm (patient #8) tumor post-treatment." (PMID 33420229, 2021). "Helical and kinase domain mutations account for about 85% of all mutations seen in PIK3CA in breast cancer." (PMID 34344439, 2021).
breast cancer (continued). "Neratinib has a synergistic antitumor effect with everolimus in PIK3CA-mutated HER2+ breast cancer patient-derived xenograft models and with trametinib in HER2-mutated HER2+ breast cancer patient-derived xenograft models." (PMID 34203351, 2021). "For example, mammary tumors of Maltese, Shih Tzu, and Yorkshire Terrier dog all have frequent PIK3CA mutation and PI3K pathway alteration." (PMID 34344882, 2021). "We found that frequency of PIK3CA H1047R mutation was 14.3% using Sanger sequencing in canine mammary tumors, and downstream molecules Akt2, p-Akt, and PTEN were dysregulated in mammary tumors when compared to normal mammary gland." (PMID 34359206, 2021). "Treatment with PI3Kα specific inhibitor alpelisib together fulvestrant increased progression-free survival of ER+ advanced breast cancer with PIK3CA mutations that had received endocrine therapy previously." (PMID 34131114, 2021). "Mutations in the p110α subunit (PIK3CA) have been found in around 40% of HR+/HER2– or HER2+ advanced breast cancer tumors and around 9% of TNBC tumors." (PMID 34026830, 2021). "The benefit of combining alpelisib and fulvestrant for HR+, HER2- advanced breast cancer with the PIK3CA mutation was further confirmed by the follow-up phase III SOLAR-1 trial." (PMID 33435254, 2021). "The activation of the PI3K pathway by gain-of-function mutations in PIK3CA occurs at a frequency of 30–40% in HR+ breast cancer patients." (PMID 33692409, 2021). "Although mutations in Akt are rare, activating mutations in the catalytic subunit of p110 PI3K (PIK3CA) have been found in breast cancer." (PMID 34298660, 2021). "It is also interesting to note that mutations of PIK3CA in ovarian and breast cancer have been associated with chemoresistance and endocrine resistance to hormonal therapy." (PMID 34440232, 2021). "Approximately 40% of the patients with hormone receptor-positive, HER2-negative breast cancer have activating mutations in PIK3CA, which encodes the catalytic subunit of PI3K, p110α, displaying hyperactivity." (PMID 34131114, 2021). "Alpelisib is a phosphoinositol-3-kinase alpha catalytic subunit (PIK3CA) inhibitor used in patients with PIK3CA mutated breast cancer." (PMID 34900474, 2021). "Arsenic and colleagues compared the results obtained by Sanger sequencing and next-generation sequencing (NGS) for PIK3CA hotspot mutations in exons 9 and 20 in 184 breast cancer samples, reporting a concordance rate of 98.4% (n = 52 mutated cases)." (PMID 33842357, 2021). "Particularly, reduced pathological complete response (pCR) rate was linked to PIK3CA mutational status in HER+ breast cancer patients who received neoadjuvant chemotherapy and anti-HER2 therapy." (PMID 34298731, 2021). "The secondary exploratory aim of this study was to evaluate the association of germline BRCA1/BRCA2 mutations with somatic PIK3CA mutations in a cohort of young and postmenopausal patients with breast cancer." (PMID 34287479, 2021). "It proved to be beneficial for patients with a PIK3CA-mutated breast cancer, thus adding the PIK3CA gene to the list of ESCAT Level 1 actionable mutations." (PMID 33924134, 2021). "A phase II study (SAFIR PI3K) is underway in patients with PIK3CA-mutated advanced breast cancer which compares Alpelisib and ER inhibitor (Fulvestrant) versus chemotherapy in these patients." (PMID 33801659, 2021). "This drug displays a promising potential on target advanced or metastatic breast cancers bearing a mutation in the PIK3CA gene, which largely encourages the field to further investigate the upstream regulation of AKT signaling." (PMID 34278744, 2021). "We were able to achieve reasonable specificity, although such thresholds will vary by technical factors, cancer type and molecular background (in our dataset, all breast cancer patients had AKT1 or PIK3CA mutations)." (PMID 34045463, 2021).
breast cancer (continued). "It is worth noting that mutations in genes in the ASCOM complex, which includes MLL3, and PIK3CA pathway mutations co‐occur in breast cancer more than we would expect by chance." (PMID 34581028, 2021). "The panel of cell lines was designed to include breast cancer models that were ER positive and/or had PIK3CA mutations (in addition to the amplified driver RTK) as these alterations are common in RTK-driven cancers." (PMID 34900714, 2021). "The experiments were performed on the MCF7 breast cancer cells characterized by the unique coding mutation in the PIK3CA gene." (PMID 33922925, 2021). "In human breast cancers, PIK3CA mutation is associated with PTEN loss and Akt activation represented by p-Akt." (PMID 34359206, 2021). "PIK3CA mutation has been found to be common in canine mammary tumors and carcinogenesis of canine mammary tumor is estrogen-dependent with estrogen receptor expression." (PMID 34359206, 2021). "These patterns mirror those observed in human breast cancers and corroborate the existence of a previously unappreciated biphasic relationship between PIK3CA allele dosage and stemness." (PMID 34762647, 2021). "Based on the SOLAR-1 study, alpelisib, in combination with fulvestrant, was approved by FDA in 2019 to treat HR+, HER2−, PIK3CA mutated breast cancers." (PMID 34769309, 2021). "The importance of the PI3K/Akt/PTEN pathway in canine mammary tumor has recently been highlighted due to the finding of frequent PIK3CA mutation." (PMID 34359206, 2021). "Most trastuzumab‐resistant breast cancer cell lines available from biobanks feature either phosphoinositide‐3‐kinase, catalytic, alpha (PIK3CA) mutation or the loss of phosphatase and tensin homolog (PTEN)." (PMID 33665980, 2021). "A phase I clinical trial investigated the effects of taselisib in patients with PIK3CA mutated breast cancer and reported a very narrow therapeutic index with a response rate of 9%." (PMID 34769309, 2021). "The PI3K inhibitor alpelisib is currently available in the clinic in combination with fulvestrant for postmenopausal women with advanced or metastatic hormone receptor-positive, HER-2-negative, PIK3CA-mutated breast cancer." (PMID 34113218, 2021). "While PIK3CA H1047R missense mutation is a frequent event in canine mammary tumors in recent studies utilizing next-generation sequencing (29–32.8%), mutation was observed in relatively low occurrence in the present study (14.3%)." (PMID 34359206, 2021). "The strengths of this study are the combined analysis of germline BRCA1/BRCA2 and somatic PIK3CA mutations in a group of postmenopausal and young patients with breast cancer." (PMID 34287479, 2021). "In agreement with our data, studies on breast cancer patients from Singapore and Peru have also found E545A to be the most frequent PIK3CA variant in tumor samples." (PMID 34287479, 2021). "We then treated different PDX models of PIK3CA mutated and WT breast cancers with the PI3K inhibitor BYL719 combined to fulvestrant and explored their effect on tumor growth as well as on both genomic and non-genomic ER pathways." (PMID 34020697, 2021). "In PIK3CA-mutated breast cancer targeted therapy with alpelisib, an α-selective phosphatidylinositol 3-kinase inhibitor is used for treatment." (PMID 34202213, 2021). "PIK3CA mutations are highly represented in ER+/HER2− breast cancer and are of clinical interest due to the availability of targeted therapy with alpelisib in the metastatic setting." (PMID 33842357, 2021). "The HER2-enriched subtype has a moderate breast cancer diagnostic accuracy, which is better than those of the presence of PIK3CA mutations, TILs, HRs, and Ki-67." (PMID 34778044, 2021).
breast cancer (continued). "Alpelisib was recently approved by the Food and Drug Administration (FDA) for use in PIK3CA-mutated breast cancer." (PMID 34084688, 2021). "Clinical efficacy was observed in patients with ovarian cancer harboring PIK3CA E545K mutations and in patients with breast cancer harboring PIK3CA H1047R and Akt1E17K mutations." (PMID 33723724, 2021). "For example, DMBA mammary tumors have mutations in Pik3ca and Pten that reflect human ER+ breast cancers." (PMID 34532657, 2021). "Attempts to enhance the G1/S arrest action are currently under clinical investigation, e.g., based on a concurrent PI3K-pathway inhibition for breast cancer (triple therapy), or a sequential use of these agents in cases bearing PIK3CA mutations." (PMID 34445095, 2021). "A recent study indicated that treatment with the PI3Kα inhibitor induced an adaptive enhanced ERα signaling by activating KMT2D, a H3K4 methyltransferase in ER+ breast cancer cells with PIK3CA mutation, indicating therapeutic resistance to PI3Kα inhibitor." (PMID 34131114, 2021). "In breast cancer, PIK3CA exon-specific mutations can enhance MAPK1/3 phosphorylation, contributing to a favorable prognosis." (PMID 34367282, 2021). "According to the Cancer Genome Atlas (TCGA) and the Catalogue of Somatic Mutations in Cancer (COSMIC), the mutation rate of the PIK3CA gene is 36% in breast cancer." (PMID 34415239, 2021). "In 2019, the PIK3CA inhibitor BYL719 (Alpelisib, Novartis) was approved by the FDA for the treatment of estrogen receptor-positive (ER+) breast cancer patients with PIK3CA mutations." (PMID 34946644, 2021). "Further stratification revealed high INPP4B expression was specifically associated with the PIK3CA-mutant ER+ breast cancer subset." (PMID 34035258, 2021). "In breast cancer, resistance to HER2‐targeting therapy can occur as a result of PIK3CA mutations, which has been reported in 15.9% of breast cancer patients." (PMID 33448107, 2021). "Four PIK3CA mutations (E545K, H1047R, E542K, and H1047L) were detected in all the breast cancer molecular subtypes." (PMID 34093841, 2021). "Mutations in PIK3CA are most common in luminal type of breast cancer, but have also been found in TNBC." (PMID 34298660, 2021). "In contrast, data from another cohort of Brazilian patients with sporadic breast cancer have reported that the most frequent PIK3CA hotspot mutations were E542K, E545K, and H1047R." (PMID 34287479, 2021). "Breast cancers often have increased activity of the so-called PI3Kα enzyme and the pathway it activates, usually attributed to genetic alterations in the PIK3CA gene, encoding a critical PI3Kα component." (PMID 34762647, 2021). "PIK3CA is the third most mutated gene in basal-like breast cancer, followed by retinoblastoma (RB) and BRCA1/2." (PMID 33435254, 2021). "We have optimized highly sensitive, specific and robust multiplex dPCR assays which allow for rapid and cost-effective absolute quantification of the most frequent pathogenic PIK3CA mutations in breast cancer, with a coverage rate of 90%." (PMID 34453076, 2021). "Mutation in PIK3CA is present in most solid tumors and is found in 12%–15% of patients with breast cancers." (PMID 34335799, 2021). "PIK3CA H1047R (c.3140A > G) has been discovered as the most common mutational hot spot in canine mammary tumor in recent studies, while the feature of PIK3CA-mutated canine mammary tumor is obscure." (PMID 34359206, 2021). "The approval of the therascreen® PIK3CA PCR assay as a companion diagnostic to detect PIK3CA gene mutations in tissue or plasma has brought the use of liquid biopsy as a diagnostic tool closer to patients with breast cancer." (PMID 34771462, 2021).
breast cancer (continued). "Similar to other breast cancer studies, PIK3CA was the most commonly mutated oncogene (31%, 15/48) in our study." (PMID 33804295, 2021). "Modeling loss of MLL3 function using shRNA knockdown in the ER+ PIK3CA‐wildtype breast cancer cell line ZR751, we found that knockdown of MLL3 led to a major loss of H3K4me1 marked peaks across the genome." (PMID 34581028, 2021). "Liquid biopsy using blood components to assess PIK3CA mutations in circulating tumor DNA (ctDNA) of patients with breast cancer has been reported by different studies." (PMID 33842357, 2021). "Although the numerous studies have defined PIK3CA mutations as oncogenic alteration, the prognostic value of PIK3CA mutations in HER2+ breast cancer patients is still ambivalent." (PMID 34842356, 2021). "On the other hand, compared with patients with PIK3CA WT status, breast cancer patients with PIK3CA mutations treated with AIs showed an improvement in time to progression." (PMID 33790792, 2021). "PI3K inhibitors are currently available and have obtained regulatory approval for ER-positive, HER2-negative breast cancers bearing PIK3CA mutations." (PMID 33435133, 2021). "Here, the analysis of MCF7 breast cancer cells revealed the presence of the DNA and RNA transcripts with the native PIK3CA mutation in the secreted exosomes." (PMID 33922925, 2021). "In this study, we provide an overview of the role of PIK3CA in breast cancer and of the characterization of its mutational status for appropriate clinical management." (PMID 33842357, 2021). "PIK3CA mutations were frequented in breast cancer (36.7%) and cervical cancer (25.14%), being specifically enriched in luminal subtype tumours." (PMID 34302033, 2021). "The rate of PIK3Ca mutations differed in the four breast cancer subtypes with 50% of luminal A, 46,7% of luminal B, 41,2% of HER2-enriched, and 28% of TNBC patients." (PMID 32210163, 2020). "It is generally agreed that chromosome 1q amplification, chromosome 16q deletion, and PIK3CA mutations are the most common pathways leading to luminal breast cancer." (PMID 32818022, 2020). "As in luminal breast cancer, this activation involves PIK3CA and AKT1 mutations to a greater extent than PTEN loss (which is more frequently reported in TNBC in general)." (PMID 32042320, 2020). "Prognostic value of PIK3CA mutation has been observed for a number of tumors, particularly for breast cancer." (PMID 33287350, 2020). "While PIK3CA-HD mutations are less potent in inducing mammary tumors, these mutations are independently associated with poor prognosis (early recurrence and death)." (PMID 31980592, 2020). "The microfluidic chip was validated for the continuous monitoring of HER-2 type breast cancer and was able to successfully detect a point mutation in phosphatidylinositol-4,5-bisphosphate 3-kinase (PIK3CA) during severe liver metastasis." (PMID 32133418, 2020). "In a serial monitoring study, we observed a significant fraction change of the H1047R mutation in phosphatidylinositol-4,5-bisphosphate 3-kinase (PIK3CA) during metastasis of the breast cancer to the liver using the ddPCR assay." (PMID 32133418, 2020). "One possible explanation is the association with the predominant type of PIK3CA mutations in breast cancer." (PMID 32176735, 2020). "Preclinical studies supported the use of the PIK3 inhibitor Taselisib in breast cancer patients bearing tumors with PIK3CA mutations, either ER+ or HER2+." (PMID 32210163, 2020). "Approval was based on SOLAR-1, a phase 3 randomized trial that showed a benefit of 5.3 months in progression-free survival with the addition of alpelisib in the cohort of patients with PIK3CA-mutated breast cancer." (PMID 32983983, 2020).